FGF23 (fibroblast growth factor 23)
Diseases named in the same sentence as FGF23 in open-access papers (continued):
Sharing a sentence is not in itself a finding about the gene and the disease.
mesenchymal tumors (continued). "Tumor-induced osteomalacia (TIO) is a debilitating syndrome caused by excessive secretion of fibroblast growth factor 23 (FGF23) from phosphaturic mesenchymal tumors, and rarely as a non-metastatic manifestation of other neoplasms." (PMID 39464221, 2024). "Tumor‐induced osteomalacia (TIO) is a rare paraneoplastic syndrome, resulting from the secretion of the phosphaturic hormone fibroblast growth factor 23 (FGF23) from a morphologically and genetically distinct tumor of soft tissue and bone, termed a phosphaturic mesenchymal tumor (PMT)." (PMID 36511653, 2023). "As a new treatment option, burosumab is available as a fully human monoclonal antibody (AK, IgG1) that specifically binds to the phosphaturic factor FGF23 in adults and children with TIO associated with phosphaturic mesenchymal tumors that cannot be curatively resected or localized." (PMID 37980279, 2023). "•Klotho is ectopically expressed in the FGF23-producing mesenchymal tumors." (PMID 30627598, 2019). "The presence of osteochondral tissues in the intraosseous tumor might be developed from undifferentiated mesenchymal cells due to high level of FGF23 produced by phosphaturic mesenchymal tumors." (PMID 28193220, 2017). "However, systemic venous sampling that detects the overproduction of FGF23 secreted by phosphaturic mesenchymal tumor has been recently recommended for the definition of tumor localization." (PMID 28193220, 2017). "Tumor-induced osteomalacia (TIO) is a rare paraneoplastic syndrome in which ectopic production of fibroblast growth factor 23 (FGF23) by non-malignant mesenchymal tumors causes phosphate wasting and bone fractures." (PMID 27468359, 2016). "Causes are thought to be due to production and secretion of proteins—phosphatonins—by mesenchymal tumours, of which FGF23, sFRP4 and FGF-7 are those identified so far (see article Physiological regulation of phosphate: klotho, FGF23 for full review)." (PMID 30393837, 2019). "Immunohistochemical studies in phosphaturic mesenchymal tumors resected from patients with documented TIO showed that HIF-1α and FGF23 were co-localized in spindle-shaped cells adjacent to blood vessels." (PMID 27468359, 2016). "FGF23 FISH testing performed to evaluate for phosphaturic mesenchymal tumor was negative." (PMID 37154160, 2023). "Therefore, it might be possible that besides mesenchymal tumors known for producing FGF-23, epithelial odontogenic tumors might be responsive for high FGF-23 levels in blood." (PMID 35204480, 2022). "Thus, acquired cases of FGF23-related hypophosphatemic osteomalacia without iron infusion therapy were presumed to be TIO with FGF23 producing tumors mainly in the bone or soft tissue, defined as phosphaturic mesenchymal tumors (PMTs)." (PMID 34901334, 2021). "Therefore, we conclude that DNA methylation does not principally regulate Klotho expression in FGF23-producing mesenchymal tumors." (PMID 30627598, 2019).
myocardial infarction (49 papers, 2013 to 2026). Gross necrosis of the myocardium, as a result of interruption of the blood supply to the area, as in coronary thrombosis. "In murine models of CHF caused by myocardial infarction or ischemia–reperfusion, it was demonstrated that FGF23 exacerbated diastolic dysfunction." (PMID 41300756, 2025). "In that way, local FGF23 possibly helps to transiently compensate the loss of contractile tissue from the infarcted area through increased contractility of the remote area after myocardial infarction." (PMID 32309615, 2019). "Furthermore, myocardial fibrosis may be induced in mice after myocardial infarction (MI) or ischemia/reperfusion by overexpression of FGF23 associated with upregulation of β-catenin, TGF-β, and procollagen I and III." (PMID 34055103, 2021). "Immediately after a heart attack, cardiac fibroblasts are responsible for generating FGF23 during the inflammatory phase through the stimulation of proinflammatory cytokines such as IL-1β and TNF-α." (PMID 41426862, 2025). "The role played by FGF23 in myocardial infarction is still unclear, although it is known that it is produced by bones." (PMID 41426862, 2025). "In models of myocardial infarction and cardiac ischemia/reperfusion, FGF23 has been shown to promote cardiac fibrosis via a beta-catenin-mediated process." (PMID 37456824, 2023). "Experimental myocardial infarction (MI) resulted in the upregulation of circulating intact FGF23 along with a suppression of vitamin D hormone levels in mice and in rat models." (PMID 35160052, 2022). "FGF23 also stimulates the proliferation of mice cardiac fibroblasts and collagen I and II synthesis, at least after myocardial infarction." (PMID 30909513, 2019). "This review summarizes the current knowledge about the role of FGF23 in ischemic heart diseases, such as myocardial infarction." (PMID 32309615, 2019). "Evidence of FGF23 stimulating cardiac fibrosis has recently demonstrated in cultured cardiac fibroblasts and in mice models of myocardial infarction and cardiac ischemic-reperfusion injury." (PMID 30200452, 2018). "In the heart, cardiac FGF23 expression is upregulated in post-myocardial infarction (MI) in rodents and mediates cardiac fibrosis through the activation of β-catenin." (PMID 29892269, 2018). "We previously reported increased serum intact Fgf23 levels in experimental myocardial infarction models." (PMID 28900153, 2017). "Previous observational studies showed that higher FGF23 was associated with higher risk of major CVDs, such as hypertension, coronary artery disease (CAD), myocardial infarction (MI), atrial fibrillation (AF), and heart failure (HF)." (PMID 34367258, 2021). "Future research should determine whether glycerol-3-phosphate or other factors derived from injured cardiomyocytes are involved in the enhanced FGF23 expression in bone cells after myocardial infarction." (PMID 34765890, 2021). "This suggests that FGF23 could potentially play a major role in healing after myocardial infarction." (PMID 32309615, 2019). "Experimental myocardial infarction in rodents induces myocardial FGF23 and skeletal FGF23 together with a rise in circulating FGF23 and the heart might therefore be capable of secreting FGF23." (PMID 31236663, 2019). "Additionally to increased FGF23 production in the bone, myocardial FGF23 was also increased on a protein and mRNA level suggesting that increased circulating FGF23 post-myocardial infarction is at least partly derived from the myocardium itself." (PMID 30013515, 2018). "This suggests that FGF23 could play a natural therapeutic role after myocardial infarction." (PMID 41426862, 2025). "In another study of patients with acute myocardial infarction admitted to Augsburg University Hospital, the results suggest that plasma FGF23 concentrations rise after this event and do not support the idea that elevated FGF23 concentrations are a risk factor for acute myocardial infarction." (PMID 41426862, 2025).
myocardial infarction (continued). "Another recent study evaluated associations between FGF23 and different outcomes, including all-cause mortality, recurrent MI, and hospitalization for HF, in participants of the TOTAL-AMI (Tailoring of treatment in all comers with acute myocardial infarction) project." (PMID 35160052, 2022). "LVH, HF, arrhythmias, myocardial infarction (MI) and vascular alterations such as stroke and vascular calcification are the most common adverse and fatal cardiac events studied in relation to FGF-23." (PMID 33767635, 2021). "Thus, this review aims to summarize the current knowledge about FGF23 in myocardial infarction." (PMID 32309615, 2019). "Recently, FGF23 has been found to promote fibrosis in injury-primed renal fibroblasts through activation of both TGFβ/Smad and FGFR4/PLCγ/calcineurin/NFAT signaling, and to cause cardiac fibrosis by upregulating β-catenin and TGFβ in vitro and after myocardial infarction in vivo." (PMID 31540546, 2019). "Furthermore, it has been recently shown that FGF23 can activate cardiac fibroblasts isolated from adult mice and newborn rats, and that the experimental elevation of FGF23 expression in an animal model for myocardial infarct further increases cardiac fibrosis." (PMID 29770125, 2018). "In addition, expression of cardiac FGF23 is also induced by CVD such as in myocardial infarction." (PMID 30200452, 2018). "Furthermore, supplementation with omega-3 (n-3) fatty acids provided a beneficial effect on kidney function in patients with a history of myocardial infarction, which may in turn reduce plasma FGF23 level." (PMID 29137111, 2017). "Indeed, our group and others could identify potential roles of FGF23 during myocardial infarction." (PMID 32309615, 2019). "However, underpathological conditions, other cell types such as immune cells in systemic inflammatoryprocesses orcardiomyocytes after experimental myocardial infarction or in patients with left ventricularhypertrophy may become relevant sources of circulating FGF23." (PMID 29096595, 2017). "FGF-23 has been shown to promote myocardial fibrosis in mice with left coronary artery ligation-induced myocardial infarction, but not in sham-operated mice." (PMID 35008591, 2021). "High intra-cardiac synthesis of FGF23 has been shown in patients with CKD and LVH as well as in animal models of experimental uremia, myocardial infarction and after pulmonary artery banding." (PMID 35118076, 2021). "Our data do not support n-3 fatty acid supplementation to reduce FGF23 levels in post-myocardial infarction patients with CKD." (PMID 29137111, 2017). "Emerging data suggest that FGF23 may also contribute to the pathophysiology of myocardial infarction (MI), but existing studies have largely focused on non-acute stages." (PMID 42041595, 2026). "Importantly, they suggested that endogenous cardiac FGF23 promotes myocardial fibrosis after myocardial infarction or ischemia reperfusion, but not under normal conditions, through induction of paracrine signaling pathways." (PMID 32315372, 2020). "Clear clinical evidence concerning the role of FGF23 during myocardial infarction is lacking." (PMID 32309615, 2019). "The main goal of the research was to determine whether FGF23 may be used as an early marker of myocardial damage among patients with T2DM and no previous history of myocardial infarction." (PMID 37371618, 2023).
Insulin resistance (48 papers, 2013 to 2025). Increased resistance towards insulin, that is, diminished effectiveness of insulin in reducing blood glucose levels. "The association of FGF-23 with atherosclerosis and CV diseases is well-documented; however, only a few previous studies have investigated its association with insulin resistance in pre-dialysis patients with CKD, and the results are contradictory." (PMID 39879508, 2025). "Deregulated FGF23 is linked to insulin resistance, pancreatic β-cell dysfunction, and systemic inflammation." (PMID 40237064, 2025). "In contrast, other studies did report associations between plasma FGF23 and insulin resistance in CKD patients." (PMID 40237064, 2025). "Since the conclusions remain discrepant, additional studies are needed to investigate the association of FGF23 with insulin resistance and its effects on carbohydrate metabolism." (PMID 38139126, 2023). "Although FGF23 is widely associated with phosphate and vitamin D metabolisms, some studies have implicated this hormone in insulin resistance." (PMID 36831188, 2023). "In previous studies, high level of FGF23 was also linked with insulin-resistance, which was related to metabolic syndrome." (PMID 31581608, 2019). "The aim of this study was to evaluate the association of FGF-23 levels with echocardiographic parameters and insulin resistance (IR) in patients with gestational diabetes." (PMID 30462803, 2018). "The objective of this study was to examine the associations of FGF23 and markers of inflammation, insulin resistance, and anthropometrics in a large cohort of community-dwelling adults." (PMID 25811862, 2015). "Higher creatinine, proteinuria, and FGF-23 levels were associated with greater insulin resistance." (PMID 39879508, 2025). "FGF23 has been associated with insulin resistance and inflammation." (PMID 37810875, 2023). "The impact of insulin deficiency and insulin resistance on FGF23 is complicated." (PMID 36084108, 2022). "In addition, we previously indicated that resistin, which mainly regulates insulin resistance, is positively associated with serum FGF23 levels in patients with T2D." (PMID 36084108, 2022). "On the contrary, insulin resistance is significantly associated with the increase of FGF23." (PMID 36084108, 2022). "Moreover, a 1-standard deviation increase in log FGF23 was associated with 8–12% increases in insulin levels and homeostatic model assessment of insulin resistance (HOMA-IR) index in both cohorts." (PMID 34208131, 2021). "In addition, FGF-23 has been associated with insulin resistant, and a recent review paper discussed the role of FGF-23 as a predictor of CV events." (PMID 34683112, 2021). "Because klotho is reportedly associated with insulin resistance, the association between FGF23 and resistin could potentially result from the effects of klotho." (PMID 30228288, 2018). "In the present population, other mechanisms that increase insulin resistance (e.g., inflammation, klotho, malnutrition, etc.)may have decreased the association between resistin and FGF23." (PMID 30228288, 2018). "Some studies evaluated the association of FGF23 with insulin resistance and DM." (PMID 28977159, 2017). "FGF23 has been shown to be associated with markers of insulin resistance, dyslipidemia, and visceral adiposity in both children and adults, suggesting that an association of FGF23 with CVD may be in part mediated by cardiometabolic disease." (PMID 25811862, 2015). "In addition, previous studies have shown a positive association between FGF-23 and insulin resistance, which can decrease insulin-stimulated protein synthesis and increase protein degradation in skeletal muscle, and may play a key role in PEW." (PMID 39839279, 2024). "Furthermore, FGF23 is positively associated with markers of insulin resistance and adiposity." (PMID 38577264, 2024).
Insulin resistance (continued). "Accordingly, blood FGF23 levels in type 1 diabetes patients with pathophysiological insulin deficiency may be high, and those in type 2 diabetes patients with hyperinsulinemia due to the fact of insulin resistance may be low." (PMID 35216490, 2022). "Moreover, FGF23 is positively associated with resistin, which is a regulator of insulin resistance." (PMID 35216490, 2022). "FGF23 may promote insulin resistance, which may influence the risk of adverse outcomes." (PMID 35216490, 2022). "FGF23 is positively associated with resistin, an adipokine, and regulator of insulin resistance, irrespective of kidney function; it should be further addressed whether this relationship is key to FGF23-induced insulin resistance." (PMID 32857288, 2020). "Although a significant relationship was found between insulin resistance and FGF-23 levels, an inverse correlation was found with P. As few studies have been conducted in this regard, further multicenter studies with larger number of patients are needed." (PMID 39879508, 2025). "They reported a relationship between insulin resistance and P balance, and found a significant and independent relationship between insulin resistance and FGF-23." (PMID 39879508, 2025). "Insulin resistance, serum FGF-23, and s-KL levels increased in patients compared with healthy individuals." (PMID 39879508, 2025). "More renal function disorders and higher serum FGF-23 levels were observed in patients with high insulin resistance." (PMID 39879508, 2025). "Increased insulin resistance development and increased serum FGF-23 and s-KL levels were observed in patients with pre-dialysis CKD when compared with healthy individuals." (PMID 39879508, 2025). "Fourth, although the relationship between FGF-23, insulin resistance, and inflammatory parameters, such as interleukin, vascular cell adhesion molecule, and tumor necrosis factor, is known, these markers have not been studied." (PMID 39879508, 2025). "Higher creatinine levels, proteinuria, and serum FGF-23 levels were observed in patients with high insulin resistance than in those with lower levels." (PMID 39879508, 2025). "Deregulated FGF23 and klotho are involved in impaired insulin signaling and insulin resistance through various potential mechanisms." (PMID 40237064, 2025). "In this study, elevated insulin resistance development and elevated serum FGF-23 and s-KL levels were observed in patients with CKD in comparison to healthy individuals." (PMID 39879508, 2025). "In contrast, another study in obese young people with or without insulin resistance observed that the group of patients with insulin resistance had lower levels of FGF23." (PMID 38732094, 2024). "Studies have shown that FGF23 regulates multiple signaling pathways in the body, affecting mineral metabolism, insulin resistance, energy balance, and premature aging." (PMID 36649363, 2023). "The study has found significantly higher levels of ctFGF23 (carboxyl-terminal FGF23) in patients with concomitant insulin resistance." (PMID 38139126, 2023). "FGF23 knockout mice presented with reduced fat mass, developed hypoglycemia and increased peripheral insulin sensitivity, and showed improved subcutaneous glucose tolerance, suggesting a link between FGF23 and insulin resistance." (PMID 31736870, 2019). "Insulin resistance has recently been reported to increase FGF23 levels, and resistin is a peptide that mainly regulates insulin resistance." (PMID 30228288, 2018). "In this study, insulin resistance significantly and independently correlated with serum carboxyl-terminal (C-terminal) FGF-23 levels." (PMID 29619868, 2018). "They identified an inverse relationship between insulin resistance and FGF-23." (PMID 39879508, 2025). "This suggests that the relationship between insulin resistance and FGF-23 levels in patients with CKD may result from mechanisms other than P metabolism." (PMID 39879508, 2025).